RNF212 (ring finger protein 212)
Description:
SUMO E3 ligase that acts as a regulator of crossing-over during meiosis: required to couple chromosome synapsis to the formation of crossover-specific recombination complexes. Localizes to recombination sites and stabilizes meiosis-specific recombination factors, such as MutS-gamma complex proteins (MSH4 and MSH5) and TEX11. May mediate sumoylation of target proteins MSH4 and/or MSH5, leading to enhance their binding to recombination sites. Acts as a limiting factor for crossover designation and/or reinforcement and plays an antagonist role with CCNB1IP1/HEI10 in the regulation of meiotic recombination (By similarity).
Synonyms: FLJ38841; SPGF62; ZHP3; formerly LOC285498
Tractability: PROTAC: ubiquitination databases record sites on it.
Gene: Protein-coding gene on chromosome 4 (1,056,250 to 1,113,564, reverse strand). Ensembl gene ENSG00000178222.
Subcellular location: Nucleus; Chromosome
Gene Ontology:
Molecular function: SUMO transferase activity
Biological process: chiasma assembly; homologous chromosome pairing at meiosis; meiotic gene conversion; reciprocal meiotic recombination; protein sumoylation
Cellular component: synaptonemal complex; chromosome; nucleus
Genetic constraint (gnomAD): Loss-of-function variants: 11 observed, 13.5 expected, observed/expected ratio (o/e) 0.82, 90% interval 0.51 to 1.35. The upper end of that interval is the gene's LOEUF score, 1.35, which puts it in group 5 of 6, group 1 being the genes least tolerant of losing a copy. Missense variants: 244 observed, 238.89 expected, observed/expected ratio (o/e) 1.02, 90% interval 0.92 to 1.14. Synonymous variants: 90 observed, 97.27 expected, observed/expected ratio (o/e) 0.93, 90% interval 0.78 to 1.1.
Homologues: Orthologues: chimpanzee RNF212 (99% identical), macaque RNF212 (65% identical), mouse Rnf212 (53% identical), rat Rnf212 (52% identical), dog RNF212 (52% identical), guinea pig Rnf212 (41% identical), tropical clawed frog RNF212 (29% identical), zebrafish rnf212 (24% identical), Caenorhabditis elegans zhp-3 (16% identical), Caenorhabditis elegans zhp-4 (14% identical), Caenorhabditis elegans zhp-2 (14% identical), Drosophila melanogaster narya (13% identical), and 2 more. Paralogues in human: RNF212B (16% identical).
Diseases named in the same sentence as RNF212 in open-access papers:
RNF212 is named in the same sentence as 10 diseases in open-access papers, as found by Europe PMC text mining. Sharing a sentence is not in itself a finding about the gene and the disease. The quoted sentences say what the papers report.
Infertility (2 papers, 2023 to 2025). "Factors that ensure crossing over between each pair of homologs include mammalian RING-domain proteins RNF212, HEI10, and RNF212B, alleles of which are linked to infertility and heritable variation in crossover rate." (PMID 39761402, 2025).
Down syndrome (1 paper, 2018). "At this study we aimed to evaluate the effects of polymorphism rs1670533 in RNF212 gene on the incidence of pregnancy in young age women who have Down syndrome baby and comparing them with pregnancy with healthy baby." (PMID 30647754, 2018).
cancer (2 papers, 2022 to 2025). A tumor composed of atypical neoplastic, often pleomorphic cells that invade other tissues. "In addition, other genes have been involved in cancer processes, such as interference with innate immune system (SH2D3C), apoptosis (BLCAP), crossing-over regulation during meiosis (RNF212), and tumor suppression (ZDHHC14, MIR138-2, and PHTF1)." (PMID 36535927, 2022).
RNF212 also shares sentences with these, for which no sentence is quoted: cervical cancer (2 papers); Legionnaires' disease (1); lung adenocarcinoma (1); Mendelian diseases (1); psoriasis (1); sarcoidosis (1); tumor (1).